ENSG00000279284 ( gene)
Diseases named in the same sentence as ENSG00000279284 in open-access papers (continued):
Sharing a sentence is not in itself a finding about the gene and the disease.
tumor (continued). "The chromatin modifier PRDM2/RIZ1 is inactivated by mutation in several forms of cancer and is a putative tumor suppressor gene." (PMID 29228717, 2017). "Based on current knowledge, it is still difficult to define HNRNPK as an oncogene or a tumor suppressor gene because of dichotomous results from clinical association data and cell line studies." (PMID 29262567, 2017). "Expression of mutL homolog 1 (MLH1), a mismatch repair gene that corrects DNA replication errors, is lost in up to 15% of sporadic tumours due to mutation or, more commonly, due to DNA methylation of its promoter CpG island." (PMID 28293327, 2017). "Several studies have suggested the role of miR-340 as tumor suppressor gene, but one report demonstrated the association between miR-340 and chemoresistance." (PMID 29050253, 2017). "Checkpoint with fork-head associated and ring finger (CHFR) is a mitotic checkpoint gene with tumor-suppressor functions." (PMID 24348823, 2014). "Our work suggests that Drosophila Rabex-5 is also a neoplastic tumour suppressor gene and that the tumour phenotype of both mutants is associated with ectopic activation of JNK and JAK/STAT pathways." (PMID 24104056, 2014). "ANX7 exhibits many biological and genetic properties of a tumor suppressor gene and is also implicated in carcinogenesis through discrete signaling pathways involving other tumor suppressors, DNA-repair and apoptosis-related genes." (PMID 22532868, 2012). "Recently, PLZF has become implicated in carcinogenesis as a tumor suppressor gene, because of its ability to regulate the cell cycle and apoptosis in many cell types." (PMID 22822476, 2012). "Emphasis should be placed on elucidating the exact relationship of TP with other angiogenic factors, HIF, signalling abnormalities, oncogene activation and loss of tumour suppressor gene function." (PMID 16317434, 2006). "Indeed, RB1 is classically and unambiguously implicated as a tumor suppressor gene for other cancer types by germline evidence." (PMID 41279109, 2025). "Even if a not negligible rate of patients with PTEN mutations do not meet diagnostic criteria for CS/PHTS, PTEN is known to be a tumor suppressor gene and the patients that show its mutation should be monitored because of the increased risk of developing malignancies." (PMID 36672590, 2022). "The role of Zbtb18 in these diseases is not well understood, but recent findings have shown that it may act as a tumor suppressor gene such that its loss may directly contribute to the development or progression of the disease." (PMID 33608456, 2021). "SLC39A10 which was down-regulated and positively associated with OS may act as a tumour suppressor gene in GBM." (PMID 32875483, 2020). "Each miRNA has a specific target mRNA, and the mRNA encoded by the tumor suppressor or tumor-promoting gene can affect the synthesis of some important cancer-associated functional proteins, so changes in mRNA expression can directly affect the occurrence of malignant tumors." (PMID 33336056, 2020). "As frequently observed for cancer-associated miRNAs, miR-494 may behave as an oncogene or a tumor-suppressor gene in a tissue-dependent manner." (PMID 29305580, 2018). "ARLTS1 is a cancer-associated gene with notable tumour suppressor properties." (PMID 28630657, 2017).
tumor (continued). "The deficiency of TIF1γ expression in a variety of tumor cells suggests that TIF1γ may play as a tumor suppressor gene in cancer development." (PMID 23676978, 2013). "Furthermore, it has been shown recently in a spontaneous model of intestinal tumorigenesis (driven by a heterozygote mutation in the tumor suppressor gene denomatous polyposis coli) that the ablation of IL-17 leads to inhibition of tumor development." (PMID 21943203, 2011). "Nearly half of these tumours arise in the context ofthe inherited predisposition syndrome, neurofibromatosis type 1 (NF1),suggesting that inactivation of the NF1 tumour suppressor gene might be causally related to the development of thesecancers." (PMID 18769552, 2008). "This suggests the target of allelic loss on 17q is a tumour-suppressor gene in this region." (PMID 7734302, 1995). "Since it is well established however that tumor development requires an accumulation of several gene mutations, we hypothesized that a potential OS suppressor function of Rptpζ can only be uncovered in the context of an already existing mutation of a common tumor suppressor gene." (PMID 26360410, 2015). "An analysis of literature data demonstrated that miRNA-23a can function both as an oncogene and as a tumor suppressor gene." (PMID 40282476, 2025). "Fumarate hydratase (FH) is an enzyme involved in the tricarboxylic acid cycle and is a tumor suppressor gene." (PMID 40362376, 2025). "LHPP functions as a tumor suppressor gene in GC by regulating the PI3K/AKT/mTOR pathway and inhibiting the Wnt/β-catenin signaling pathway, the TGFβ/Smad signaling pathway, AKT phosphorylation, and other mechanisms to suppress tumor occurrence and progression." (PMID 40240758, 2025). "GSDME is a key protein in the switch between apoptosis and cellular pyroptosis and has been identified as a potential tumor suppressor gene." (PMID 40756987, 2025). "We confirmed through machine learning residual analysis that TNNC1 is significantly downregulated in LUAD tissues, consistent with its function as a tumor suppressor gene." (PMID 40433361, 2025). "SOD2 is a mitochondrial antioxidant gene that can be upregulated by the UPRmt, and it exhibits both tumor-suppressive and tumor-promoting functions through scavenging superoxide and regulating hydrogen peroxide levels." (PMID 41154474, 2025). "miR-34c, a member of the miR-34 family, has been extensively investigated in cancer research as a tumor suppressor gene." (PMID 39129166, 2025). "In this study, we observed that NDRG1 exhibits an independent association with a more favorable prognosis in SKCM, suggesting its potential role as a tumor suppressor gene." (PMID 41409301, 2025). "Discovered over 20 years ago as a “candidate tumor suppressor gene”, PTEN is an enzyme that is strictly regulated and capable of dephosphorylating both protein and lipid substrates." (PMID 40463389, 2025). "If the target of ncRNAs is an oncogene, ncRNAs can be considered a tumor-inhibiting factor; if the target of ncRNAs is a tumor suppressor gene, ncRNAs can be considered an oncogenic factor." (PMID 40296912, 2025). "AMBRA1 regulates multiple pathological processes in cancer cells, but the specific role it plays depends on the tumour microenvironment and genetic background, indicating that it can act as an oncogene or a tumour suppressor gene." (PMID 40464146, 2025).
tumor (continued). "The results of this study suggested that CYLD acted as a tumor suppressor gene in PCa and promoted cell ferroptosis through Hippo/YAP signaling." (PMID 38246916, 2024). "ERBB4 is also the only member of the EGFR family that can function as either an oncogene or a tumor suppressor gene." (PMID 37855863, 2024). "Collectively, these results indicate that SESN1 is a downstream target of MYCN and functions as a tumor suppressor gene in NB." (PMID 38516781, 2024). "Our KEGG enrichment analysis of the transcriptome data also demonstrated that circSPECC1 functions as a tumor suppressor gene in GBM by primarily influencing the PI3K-AKT signaling pathway." (PMID 39333871, 2024). "Previous studies have suggested that TRIAP1 functions as a tumor-promoting gene, whereas LC3B acts as a tumor suppressor gene." (PMID 38769122, 2024). "VEGF is a hypoxia-responsive gene that plays a key role in the development of tumor neovascularization." (PMID 38200568, 2024). "Apart from its role as a cell cycle regulator, p21 regulates DNA replication, repair, and apoptosis, and inhibits tumor growth as a tumor suppressor gene." (PMID 39684919, 2024). "In the context of tumor cells, Egr1 plays a dual role, functioning as both a tumor suppressor gene and a tumor-promoting gene." (PMID 38672136, 2024). "KCNQ1 has also been demonstrated to act as a tumor suppressor gene in some gastrointestinal cancers." (PMID 38807370, 2024). "It has been shown that pharmacological activation of PTEN, a potent tumor suppressor gene, can dominantly antagonize the proto-oncogenic phosphoinositide 3-kinase (PI3K)–AKT signaling pathway with acceptable side effects." (PMID 39502780, 2024). "Taken together, these findings suggest that hnRNPA1 plays a different regulatory role and acts as a tumor suppressor gene in AGS and Kato III cells by regulating the formation of RONΔ160." (PMID 38268030, 2024). "As a functional DDR is critical for maintaining genome integrity and preventing tumor development, SETD2 is considered as a putative tumor suppressor gene in cancers." (PMID 37759431, 2023). "The human fragile histidine triad (FHIT) gene is a tumor suppressor gene, and heterozygous deletion (LOH), homozygous deletion, and abnormal expression of the FHIT gene have been implicated in several types of human malignancy." (PMID 37749550, 2023). "NLRP3 also has been reported in a multitude of studies to be involved in tumor growth and development both as an oncogene and as a tumor suppressor gene." (PMID 37449203, 2023). "There is solid evidence that TPM1 can act as a tumor-suppressor gene in oral squamous cell carcinoma (OSCC)." (PMID 37686101, 2023). "Unlike other cyclins, which positively regulate the cell cycle, cyclin G2 (CCNG2) regulates cell proliferation as a tumor suppressor gene." (PMID 37204480, 2023). "In this context, our study indicated the expression of function of a tumor-promoting gene, METTL13, in GC for the first time." (PMID 35925508, 2023). "According to earlier studies, TUSC7 can serve as a tumor suppressor gene in several tumors via inhibiting the expression of such miRNAs as miR-10a, miR-211 and miR-23b." (PMID 38054829, 2023). "As a tumour suppressor gene, PTEN is a key negative regulator of the PI3K/AKT pathway, which is involved in regulating cell biological processes such as cell proliferation, invasion, and cycle arrest." (PMID 36908850, 2023). "The PRDM5 protein was found to have a variety of functions as a transcription factor, being involved as a tumor suppressor gene in epithelial cancer and as a regulator of extracellular matrix development in corneal and bone cells." (PMID 37629506, 2023). "Our previous experiments confirmed that NCX2 inhibited the growth of U87 cells in nude mice, indicating that NCX2 is a potential tumor suppressor gene." (PMID 36334237, 2023).
tumor (continued). "Previous studies pointed out the potential of DAB2 as a tumor suppressor gene since a decrease in DAB2 expression was observed in a wide range of tumors." (PMID 37510211, 2023). "Although studies have shown the role of TBX2 as a tumor suppressor gene, there is some evidence correlating the overexpression of TBX2 in NSCLC." (PMID 37324026, 2023). "Studies have shown that p38MAPK acts as a tumor suppressor gene, negatively regulating cell cycle progression and inducing cell cycle arrest in the G2/M phase, as well as apoptosis." (PMID 37476197, 2023). "Growing evidence in recent years has demonstrated that METTL3, an m6A methyltransferase that functions as both an oncogene and a tumor suppressor gene, plays an important role in various cancers development." (PMID 38012763, 2023). "In different solid tumors and in diverse tumor cell lines, MEG3 overexpression inhibits proliferation, hence it is used as a tumor suppressor gene." (PMID 37388937, 2023). "In vitro, we found that PTGIS was a tumor-promoting gene of LUSC and HRASLS was a tumor-suppressor gene." (PMID 36703911, 2023). "Mounting evidence showed that RRAD is important for the progression and metastasis of tumor cells, which play opposite roles as an oncogene or tumor suppressor gene depending on cancer and cell type." (PMID 36979412, 2023). "Theories of malignant transformation include synergistic effect of smoking and HPV infection, abnormal expression of genes such as tumor suppression gene." (PMID 37069678, 2023). "Taken together, these results reveal that PCBP1 acts as a tumour suppressor gene, inhibiting the tumorigenesis of LUAD." (PMID 35907982, 2022). "Inhibitor of growth family member 4 is a candidate tumour suppressor gene that exerts the tumour‐suppressive effect via multiple pathways in various tumours." (PMID 35075768, 2022). "Exogenous expression of the EMP3 gene has been found to limit tumor cell proliferation and act as a tumor suppressor gene." (PMID 35982458, 2022). "Although ZNF320 and CD8+ T cell infiltration are associated, we found that ZNF320 is positively correlated with the immune checkpoint gene, cannot produce tumor killing benefits, and is actually involved in immune escape." (PMID 36287187, 2022). "Based on the findings, including the results of in vitro tests, it was observed that DIRAS2 is a tumor suppressor gene for SKCM, with the Wnt/β-Catenin signaling pathway being the negatively regulated target." (PMID 35651810, 2022). "Recent studies have demonstrated that zinc-finger protein 677 (ZNF677) acts as a tumor suppressor gene in cancer." (PMID 35164660, 2022). "Recent studies have shown that the absence of SIRT1 can cause sphingomyelin to accumulate in cells, and in different cancer types or under different experimental conditions, SIRT can act as an oncogene or a tumor suppressor gene." (PMID 35846357, 2022). "MicroRNAs (miRNAs) play a role in the development and progression of cancer as an oncogene or tumor suppressor gene." (PMID 35147974, 2022). "Our findings differ from previous publications, one of which touted Notch1 as a tumor-promoting gene, whereas the other concluded Notch1 is a tumor-suppressor gene." (PMID 36970723, 2022). "GSDME was shown to be sensitive to a number of anti-neoplastic drugs among others, which is reported to be suppressed via epigenetic inactivation in various cancers and considered as a tumor suppressor gene." (PMID 36605187, 2022). "AHRR encodes the aryl hydrocarbon receptor repressor (AhRR), which acts as a tumor suppressor gene in multiple human cancers." (PMID 35778420, 2022). "ATAC-seq reveals that it induces EPHA3, which is a tumor neoantigen and tumor-suppressor gene, thus demonstrating a novel mechanism of action." (PMID 35624662, 2022). "RDH16 is a tumor-suppressing gene, and it had been reported that downregulation of RDH16 occurs in approximately 90% of primary HCC patients with poor prognosis." (PMID 35646665, 2022).
tumor (continued). "Overall, our study demonstrated that LHPP function as a tumor suppressor gene in GC by regulating the PI3K/AKT/mTOR pathway." (PMID 36484014, 2022). "The GTP-binding protein Di-Ras3 (DIRAS3) has been established as a maternally imprinted tumor suppressor gene." (PMID 35170376, 2022). "Recently, it has been verified that miR-153, as a tumor suppressor gene, regulates angiogenesis by modulating VEGF and ANG1 in glioma and breast cancer, respectively." (PMID 36158686, 2022). "Taken together, these results show that PCBP1 acts as a tumour suppressor gene, inhibiting the tumorigenesis of LUAD." (PMID 35907982, 2022). "TXNIP is a thioredoxin-binding protein involved in redox regulation and glucose uptake that functions as a tumor suppressor gene." (PMID 36137002, 2022). "Recent studies have highlighted the possible role of TRIM58 as a tumor suppressor gene, which degrades β-catenin through ubiquitination, resulting in the inactivation of β-catenin signaling." (PMID 36461099, 2022). "Lnc-RAB11B-AS1 is reported to be dysregulated in several types of cancers and can function as both an oncogene and tumor suppressor gene." (PMID 36359911, 2022). "This review presents a study on the mechanistic roles of miR-153 as either a tumor suppressor gene or an oncogene in proliferation, apoptosis, migration and invasion, metastasis, angiogenesis and chemo/radio resistance ability of cancer cells." (PMID 36158686, 2022). "MiR‐133b has been identified as a tumour suppressor gene in a variety of cancers, and is closely related to suppressed tumour metastasis." (PMID 35638462, 2022). "Zinc finger, DHHC-type containing 2 (ZDHHC2), proposed as a putative tumour/metastasis suppressor gene and was often aberrantly decreased in human cancers." (PMID 35057823, 2022). "This suggests that SMIM3 has complex regulatory roles, and can act as either a potential oncogene or a tumor suppressor gene in different cancer types." (PMID 36550462, 2022). "Second, the number of included studies on circRNA, a tumor suppressor gene, is relatively small, and more studies need to be conducted in the future, to further confirm the results." (PMID 35595945, 2022). "Pituitary tumor-transforming gene-1 (PTTG1), one type of DNA repair-related gene, has been reported to be dysregulated in several tumors and serve as a tumor promotor." (PMID 35251171, 2022). "Our current study supports a role for ZNF148 as a tumor suppressor gene in metastatic TNBC, that is actively repressed by MYC." (PMID 36207293, 2022). "At early stages, TGFβ suppresses tumor growth, acting as a tumor suppressor gene, while during latest stages and in metastasis TGFβ enhances tumor growth and promotes angiogenesis, migration, and invasion." (PMID 36338516, 2022). "Interferon regulatory factor-5 (IRF5) is a transcription factor and has essential cellular mechanisms as a tumor suppressor gene." (PMID 35410350, 2022). "BLM helicase has been implicated in various DNA transactions where it acts as a bonafide tumor suppressor gene." (PMID 33777104, 2021). "Another valuable finding from our studies was that estrogen also upregulated a tumor-suppressor gene, IL-24, only in GS3." (PMID 34944995, 2021). "CA9, a well-known hypoxia-induced gene, plays critical roles in promoting tumor progression and hypoxia adaptation." (PMID 34493285, 2021). "It acts as an oncogene in some tumors to mediate the tumor process, while in others it plays a role as a tumor suppressor gene." (PMID 34356052, 2021). "In this paper, we examined the status of GNMT, a gene identified in our previous studies as a putative tumor-suppressor gene and biomarker for PC." (PMID 33802396, 2021).